GABRA2 (gamma-aminobutyric acid type A receptor subunit alpha2)
Diseases named in the same sentence as GABRA2 in open-access papers (continued):
Sharing a sentence is not in itself a finding about the gene and the disease.
epilepsy (15 papers, 2014 to 2025). A brain disorder characterized by episodes of abnormally increased neuronal discharge resulting in transient episodes of sensory or motor neurological dysfunction, or psychic dysfunction. "In contrast, variants in GABRA2 are an exceedingly rare cause of epilepsy, with only eight reported cases to date." (PMID 39737842, 2025). "This case offers valuable insights into the structure–function relationships within the extracellular domain and contributes to the limited existing literature on the genotype–phenotype correlation for GABRA2‐associated epilepsy." (PMID 39737842, 2025). "Several epilepsy modifier genes, including CACNA1G and GABRA2, were first identified in the Scn1a+/− mouse model of Dravet syndrome and later confirmed as epilepsy risk genes in humans." (PMID 34086081, 2021). "We conclude that altered expression levels of known epileptic risk factors such as Nav1.1, Nav1.2, Nav1.6 and GABRA2 result in enhanced seizure susceptibility and manifestation of epilepsy in the hippocampus." (PMID 29046322, 2017). "Multiple genome‐wide association studies identified noncoding single‐nucleotide polymorphisms in GABRA2 associated with increased risk for epilepsy (International League Against Epilepsy Consortium on Complex Epilepsies, 2014, 2018), as well as alcohol dependence and brain oscillations." (PMID 32347641, 2020). "The gene encoding the α2 subunit (GABRA2) was identified as one of the most likely biological epilepsy genes in a recent genome-wide mega-analysis (The International League Against Epilepsy Consortium on Complex Epilepsies, 2018)." (PMID 31297048, 2019). "Strikingly, Gabra2, which has been linked to epilepsy in humans, was upregulated twofold." (PMID 29046322, 2017). "We observed rescue of seizure, survival and neuronal phenotypes with this single nucleotide repair, validating Gabra2 as an epilepsy modifier gene." (PMID 34086081, 2021). "The largest GWAS of oscillatory power during eyes-closed resting EEG to date found through a gene-based approach that GABRA2, a known genetic marker for alcohol abuse disorder and epilepsy, was significantly related to β wave power." (PMID 33218114, 2020). "For many years, GABRA2 (MIM: 137,140), that encodes for the GABAAR subunit α2 (GABAAR α2), remained as a candidate gene for epilepsy." (PMID 32347641, 2020). "After searching in DrugBank, we retrieved a total of 47 anti-epileptic drugs and 151 targets, of which identified 17 target genes (CACNA1A, CHRNA4,CHRNA7,GABRA1,GABRA2,GABRB2,GABRG2,GRIK1,GRIN1,GRIN2B,KCNQ2,KCNQ3,SCN1A,SCN2A, SCN3A,SCN8A and SCN9A) were overlapped with risk genes of epilepsy." (PMID 36006933, 2022). "Considering the significance of GABAergic pathways in relation to epilepsy, strain-specific expression of Gabra2 may differentially influence excitatory/inhibitory balance." (PMID 27768696, 2016). "Altered GABRA2 transcript and protein expression has observed in a number of rodent seizure models and patients with focal cortical dysplasia, tuberous sclerosis and temporal lobe epilepsy, suggesting a potential link between GABRA2 expression and epilepsy." (PMID 27768696, 2016). "Thus, natural variation in GABRA2 expression may contribute to variable expressivity of Dravet syndrome and other epilepsy phenotypes, and possibly contribute to treatment response for drugs that target GABAA receptors." (PMID 34086081, 2021). "Gabra2 repair restored transcript and protein expression, increased abundance of α2-containing GABAA receptors in hippocampal synapses, and rescued epilepsy phenotypes of Scn1a+/− mice." (PMID 34086081, 2021). "However, to date, no GABRA2 genetic variants have been associated with human epilepsy." (PMID 27768696, 2016). "Additionally, many studies suggest that deficits in the GABAA receptors such as GABRA2 and GABRA5 contribute to central nervous system disorders such as anxiety disorders, epilepsy, schizophrenia, and insomnia." (PMID 37355705, 2023).
epilepsy (continued). "Additionally, it normalizes aberrant spine morphology in Gabra2-1 pups without affecting wildtype controls, supporting its potential as a safer, more targeted treatment for pediatric epilepsy." (PMID 40993379, 2025).
schizophrenia (8 papers, 2007 to 2024). A major psychotic disorder characterized by abnormalities in the perception or expression of reality. "It has been shown that the expression of the GABRA2 gene is dysregulated in several neuropsychological conditions such as autism spectrum disorder, schizophrenia, depression, and impulsive behavior." (PMID 36012404, 2022). "We sought to determine relative levels of GABRA1, GABRA2, GABRA3, and GABRA5 mRNAs, GABRA3 protein levels, and to determine cellular location of GABRA3 protein in the midbrain in schizophrenia." (PMID 34174930, 2021). "In addition, we found that GABRA3 and GABRA2 mRNAs were highly positively correlated with TH and DAT mRNAs in schizophrenia cases but not controls." (PMID 34174930, 2021).
alcohol use disorder (6 papers, 2012 to 2025). "Further, GABRA2 gene variants were also associated with impulsive behaviours measured in an incentive delay task, which increases the risk of development and relapse of alcohol use disorders." (PMID 36422192, 2022). "Furthermore there is considerable evidence that polymorphisms in the Gabra2 subunit are associated with alcohol use disorder (and references therein)." (PMID 25652416, 2015). "This study contributes to the increasing literature on the effect of GABRA2 on behaviors characterized by poor effortful control, namely externalizing behavior in adolescence and impulsive personality in adults, both risk factors for alcohol use disorder (AUD)." (PMID 25365806, 2014). "Nearby genes include GABRA2, for which a significant body of work suggests a link to alcohol use disorder." (PMID 28261068, 2017). "Previous research related GABRA2 genetic variants, but not methylation patterns to endophenotypes of alcohol response and alcohol use disorder risk." (PMID 36422192, 2022). "Whilst genetic variations of the GABRA2 gene in humans have previously implicated this subunit in ethanol abuse, current data suggest that this is unlikely to be due to GABAergic manipulations directly changing motivational behaviour." (PMID 23115637, 2012).
cocaine addiction (5 papers, 2012 to 2025). "Since deleting α2-GABAA receptors in mice abolishes cocaine’s ability to facilitate responding for a conditioned reinforcer, we suggested that these findings might provide an approach to understanding the association between GABRA2 variants and human cocaine addiction." (PMID 26635556, 2015). "We and others have previously reported an association between variants of the GABRA2 gene, encoding the α2 subunit of GABAA receptors, and human cocaine addiction." (PMID 26635556, 2015).
autism (4 papers, 2014 to 2024). Persistent deficits in social interaction and communication and interaction as well as a markedly restricted repertoire of activity and interest as well as repetitive patterns of behavior. "Some features were explained by the FLNA gene reverse phenotyping; but autism and seizures could be explained by the GABRA2 variant; thereby suggesting possibility of a blended phenotype." (PMID 39263390, 2024). "The GABA receptor gene cluster at this locus has previously been implicated in autism, and GABA(A) receptors including GABRA2 have been reported to be significantly down-regulated in brains of autism subjects." (PMID 24699272, 2014).
Dravet syndrome (4 papers, 2016 to 2022). "This work has clear therapeutic implications and suggests that interventions that increase CNS expression or function of GABRA2 should improve outcomes in Dravet syndrome." (PMID 34086081, 2021). "Identification of Gabra2 as a putative modifier gene at the Dsm1 locus furthers our understanding of the genetic basis of Dravet syndrome." (PMID 27768696, 2016). "The studies identified several genetic modifiers such as Hlf, the gene encoding hepatic leukemia factor, Cacna1g, the gene encoding Cav3.1 and Gabra2, the gene encoding the GABAA receptor α2 subunit that influence the phenotypes and severity of Scn1a+/− mouse model of Dravet syndrome." (PMID 35571373, 2022). "Interestingly, clobazam, which has preferential affinity for the GABRA2 subunit, offers some therapeutic benefit in Dravet syndrome patients." (PMID 27768696, 2016).
cocaine abuse (3 papers, 2014 to 2023). Disorders related or resulting from use of cocaine. "In support, we reported that haplotypes of the Gabra2 gene encoding the GABAAR α2-subunit are associated with cocaine abuse in addicts." (PMID 30138693, 2018). "•Gabra2 gene variations coupled with childhood trauma associate with cocaine abuse." (PMID 30138693, 2018). "Although our findings are at one level surprising, they may be consistent with data from human studies that suggest that variations in the GABRA2 gene are linked to cocaine abuse only when in combination with early life traumatic events." (PMID 24481569, 2014).
dependence (3 papers, 2012 to 2023). "Gabra2 encodes the GABAA receptor α2 subunit, which has previously been associated with addiction and dependence." (PMID 27768696, 2016).
drug dependence (3 papers, 2008 to 2021). "GABRA2 also affects illicit drug dependence in their sample in both adolescence and later life stages." (PMID 20179766, 2010). "Functionally restoring Gabra2 expression decreased methamphetamine stimulant sensitivity and supports preclinical and human genetic studies implicating the GABA-A receptor in psychostimulant addiction-relevant traits." (PMID 34677900, 2021).
insomnia (3 papers, 2019 to 2024). A sleep disorder characterized by difficulty in falling asleep and/or remaining asleep. "GABRA1 and GABRA2 are the components of the heteropentameric receptor for GABA, receptor of GABA (gamma-aminobutyric acid) that is an important inhibitory neurotransmitter in vertebrate brain and plays an essential role in the treatment of insomnia by inhibiting brain neurotransmitters excitement." (PMID 30891080, 2019).
sleep disorder (3 papers, 2019 to 2024). A change from the patient's baseline sleeping pattern, in the hours slept and/or an alteration/dysfunction in the stages of sleep. "Furthermore genes associated with gamma-aminobutyric acid (GABRA2, GABRB) have been implicated in sleep disorders including ApoB." (PMID 32000760, 2020).
cervical cancer (2 papers, 2019 to 2021). A primary or metastatic malignant neoplasm involving the cervix. "GABRA2 was a cervical cancer‐specific marker and could be used for diagnosis, which may boost the development of new epigenetic therapies." (PMID 33350104, 2021). "Moreover, we identified four cervical cancer-specific methylation markers, cg07211381 (RAB3C), cg12205729 (GABRA2), cg20708961 (ZNF257), and cg26490054 (SLC5A8), with 96.2% sensitivity and 95.2% specificity by using the tenfold cross-validation of TCGA data." (PMID 31871774, 2019). "We identified four cervical cancer-specific methylation markers, including cg07211381 (RAB3C), cg12205729 (GABRA2), cg20708961 (ZNF257), and cg26490054 (SLC5A8), and the significantly decreased expression of GABRA2, ZNF257, and SLC5A8 in CSCC was further confirmed in human CSCC tissues by IHC." (PMID 31871774, 2019).
developmental and epileptic encephalopathy (2 papers, 2023 to 2025). An epilepsy associated with developmental impairment that may be due to either the underlying etiology or the superimposed epileptic activity, or both. "Variants in the GABRA2 gene, which encodes the α2 subunit of the γ‐aminobutyric acid A receptor, have been linked to a rare form of developmental and epileptic encephalopathy (DEE) referred to as DEE78." (PMID 39737842, 2025).
early-onset epileptic encephalopathy (2 papers, 2020 to 2024). "Recently, six missense variants in GABRA2, a member of this family, have been associated with early infantile epileptic encephalopathy (EIEE)." (PMID 32347641, 2020). "Recently, six missense variants in GABRA2 have been reported to cause early infantile epileptic encephalopathy (EIEE): five were de novo and one was present in two affected siblings, inherited from a father who also presented the variant at low level in blood, indicating mosaicism." (PMID 32347641, 2020).
heroin addiction (2 papers, 2018 to 2025). "In line with previous studies, we provided evidence of the association between GABRA2 rs279858 and variants in the rs279858-linked low-expression haplotype block with heroin addiction vulnerability." (PMID 30061709, 2018). "We discovered that GABRA2 rs279858-linked variants were associated with heroin addiction vulnerability as well as the connective strength of the reward network." (PMID 30061709, 2018). "Prospective and/or follow-up studies are needed to determine the causal role of GABRA2 rs279858 in the reward circuit in heroin addiction." (PMID 30061709, 2018). "The GABRA2 rs279858-linked SNPs were associated with susceptibility to heroin addiction by affecting the connections of the reward circuit and cognition." (PMID 30061709, 2018). "Variants in the GABAergic pathway also display risk signals that are specific to ethnicity: GABRA2 rs11503014 has been linked to heroin addiction in African American individuals, while polymorphisms in GAD1 show significant associations within Han Chinese groups." (PMID 40993075, 2025). "Consequently, we validated the association between GABRA2 rs279858 and heroin addiction in 1032 HAs and 2863 HCs." (PMID 30061709, 2018).
mental disorder (2 papers, 2019 to 2022). A disease that has its basis in the disruption of mental process. "The core targets of SHR during the treatment of mental disorders were GABRA1, GABRA2, GABRA3, GABRA5, and GABRA6, involving synaptic transmission and transmembrane movement." (PMID 39280954, 2022).
mood disorder (2 papers, 2019 to 2024). A cognitive disorder a disturbance in which the person's mood is hypothesized to be the main underlying feature. "The GABRA2 gene encodes the α2 subunit of α-containing GABAA receptors, which have been linked to mood disorders and CNS diseases such as Alzheimer." (PMID 37982563, 2024). "In contrast, our study probed the role of natural variation in the level of Gabra2 in the context of an isogenic B6J background and profiled the expression of all major GABA-A subunits in cortex, striatum, and hippocampus—regions involved in different aspects of memory, mood disorders and addiction." (PMID 30984232, 2019).
nicotine addiction (2 papers, 2023). "The GABRA2 and GABRG2 genes were related to three signaling pathways, including hsa05033, nicotine addiction; hsa04727, GABAergic synapse; and hsa05032, morphine addiction." (PMID 37324729, 2023).
Obesity (2 papers, 2014 to 2024). Accumulation of substantial excess body fat. "The genes NPY and GABRA2 have been previously found associated with obesity and food intake, being involved in multiple central nervous system functions regulation, while TPMT has an important role in drug metabolism." (PMID 24548628, 2014). "Variations in the gamma-aminobutyric acid receptor subunit alpha-2 (GABRA2) and GRB2-associated binding protein 2 (GAB2) genes are linked to behavioural problems, substance use, drinking behaviour, and obesity." (PMID 38674857, 2024).
adenomyosis (1 paper, 2022). The growth of endometrial tissue inside the muscular wall of the uterine corpus. "Decreased expression of GABRA2 in the myometrium of adenomyosis women and further definition of the different subunits that confer tissue-specific expression may provide potential targets for drug development and underpin future mechanistic studies aimed to minimize pain associated with adenomyosis." (PMID 35773139, 2022).
astrocytoma (1 paper, 2010). "Transcripts exhibiting significant under expression in trisomic BG01V APCs and CCF-STTG1 astrocytoma cells relative to diploid H9 APCs include several markers of normal differentiated astrocytes, including TRPA1, GABRA2, BDNF, BDKRB1 and BDKRB2." (PMID 20423517, 2010).
cognitive decline (1 paper, 2021). "The expression of GABRA2 in the frontal cortex is associated with cognitive decline." (PMID 33920826, 2021).
colon adenocarcinoma (1 paper, 2022). "Ling Yan and colleagues showed that overexpression of GABRA2, GABRA3, GABRB3, GABRG2, GABRG3, GABRD, and GABRE might be diagnostic for colon adenocarcinoma." (PMID 35565356, 2022).
Epileptic encephalopathy (1 paper, 2025). A condition in which epileptiform abnormalities are believed to contribute to the progressive disturbance in cerebral function. "In conclusion, we have presented a case of developmental and epileptic encephalopathy in a male patient from China, who was found to possess a novel de novo heterozygous variant in the extracellular domain of GABRA2." (PMID 39737842, 2025).
glioma (1 paper, 2024). A benign or malignant brain and spinal cord tumor that arises from glial cells (astrocytes, oligodendrocytes, ependymal cells). "We previously reported that high levels of GABRA2, GABRA3, GABRB3, GABRG1, and GABRG2 indicated better prognosis in glioma, and GABRB3 was particularly associated with longer OS in patients with lower-grade gliomas." (PMID 39595908, 2024).
neuroblastoma (1 paper, 2022). Neuroblastoma (NB) is the most common solid, extracranial childhood tumor. "GABRA2 methylation of 4 CpG sites in the CpG island was compared to neuroblastoma cells which were exposed to 100 mM of ethanol for 2, 5 and 9 days, followed by a withdrawal interval of 4 days." (PMID 36422192, 2022). "Further, GABRA2 methylation patterns were analysed in neuroblastoma cells under ethanol exposure and withdrawal." (PMID 36422192, 2022). "Similarly, neuroblastoma cells are expected to undergo significant changes in GABRA2 CpG methylation during ethanol exposition over 9 days and subsequent alcohol withdrawal." (PMID 36422192, 2022). "These neuroblastoma cells, such as fibroblasts, may have low levels of methylation at the GABRA2 site." (PMID 36422192, 2022). "No significant changes in the same GABRA2 CpG site methylation patterns were found in neuroblastoma cell lines which were exposed to alcohol over a period of 9 days and subsequent ethanol withdrawal." (PMID 36422192, 2022). "No methylation was observed in the four GABRA2 CpG sites in the incubated neuroblastoma cells." (PMID 36422192, 2022). "Furthermore, we could not detect any effect of ethanol on the GABRA2 methylation pattern in neuroblastoma cells." (PMID 36422192, 2022).
renal cell carcinoma (1 paper, 2015). "We observed a particularly large effect in renal cell carcinoma where there is a ten-fold median decrease in GABRA2 alongside a six-fold increase in expression of GABRD." (PMID 26555223, 2015).
cancer (4 papers, 2019 to 2025). A tumor composed of atypical neoplastic, often pleomorphic cells that invade other tissues. "Throughout cancer staging, TCGA database showed consistent reduction in expression levels of GABRA2, GABRE, GABRG1 and GABRP by up to 32.7%, 18.7%, 15.4% and 5.9%, respectively." (PMID 40583063, 2025). "Among all these 5 DNA, GBP4, GABRA2, and RIPPLY2 were once reported in cancer research." (PMID 33350104, 2021).
tumor (2 papers, 2019 to 2024). "Genes GABRA2 and GABRB3 had a Bonferroni-adjusted p value < 0.05 in these tumor samples." (PMID 38539663, 2024).